SNCG (synuclein gamma)
Description:
Plays a role in neurofilament network integrity. May be involved in modulating axonal architecture during development and in the adult. In vitro, increases the susceptibility of neurofilament-H to calcium-dependent proteases (By similarity). May also function in modulating the keratin network in skin. Activates the MAPK and Elk-1 signal transduction pathway (By similarity).
Synonyms: SR; BCSG1; PERSYN
Tractability: No criterion of Open Targets' tractability assessment is met for any kind of drug.
Gene: Protein-coding gene on chromosome 10 (86,955,771 to 86,963,261, forward strand). Ensembl gene ENSG00000173267.
Subcellular location: Cytoplasm, perinuclear region; Cytoplasm, cytoskeleton, microtubule organizing center, centrosome; Cytoplasm, cytoskeleton, spindle
Subcellular location (Human Protein Atlas): Centrosome; Cytosol; Golgi apparatus
Gene Ontology:
Molecular function: protein binding; cuprous ion binding
Biological process: chemical synaptic transmission; synapse organization; synaptic vesicle endocytosis; protein secretion
Cellular component: centrosome; cytoplasm; cytosol; extracellular exosome; axon terminus; neuronal cell body; axon; perinuclear region of cytoplasm; spindle
Genetic constraint (gnomAD): Loss-of-function variants: 13 observed, 15.26 expected, observed/expected ratio (o/e) 0.85, 90% interval 0.55 to 1.35. The upper end of that interval is the gene's LOEUF score, 1.35, which puts it in group 5 of 6, group 1 being the genes least tolerant of losing a copy. Missense variants: 143 observed, 160.69 expected, observed/expected ratio (o/e) 0.89, 90% interval 0.78 to 1.02. Synonymous variants: 61 observed, 64.9 expected, observed/expected ratio (o/e) 0.94, 90% interval 0.76 to 1.16.
Homologues: Orthologues: chimpanzee SNCG (96% identical), macaque SNCG (94% identical), rabbit SNCG (91% identical), pig SNCG (90% identical), dog SNCG (87% identical), mouse Sncg (83% identical), guinea pig SNCG (76% identical), rat Sncg (76% identical), tropical clawed frog sncg (68% identical). Paralogues in human: SNCB (54% identical), SNCA (54% identical).